WDR81 (WD repeat domain 81)
Diseases named in the same sentence as WDR81 in open-access papers:
WDR81 is named in the same sentence as 34 diseases in open-access papers, as found by Europe PMC text mining. Sharing a sentence is not in itself a finding about the gene and the disease. The quoted sentences say what the papers report.
cerebellar ataxia (10 papers, 2012 to 2025). A neurological syndrome characterized by clumsy and uncoordinated movement of the limbs, trunk, and cranial muscles. "Pathogenic variants in the WDR81 gene located on chromosome 17p13.3 are associated with cerebellar ataxia, impaired intellectual development, and disequilibrium syndrome-2 (CAMRQ2)." (PMID 40013199, 2025). "Lastly, WDR81 mutations have been associated with developmental disorders including cerebellar ataxia, mental retardation, quadrupedal locomotion syndrome (CAMRQ2), and microcephaly." (PMID 39192051, 2024). "WDR81 is necessary for Purkinje and photoreceptor cell survival and has been reported to be associated with cerebellar ataxia and mental retardation." (PMID 35990977, 2022). "Mutations in WDR81 are associated neurological disorders including CAMRQ2 (cerebellar ataxia, cognitive disability, and disequilibrium, MIM 610185), sever microcephaly and HYC3." (PMID 33724704, 2021). "Mutations in the gene encoding the WD40 repeat-containing protein WDR81 are associated with neurological disorders, including cerebellar ataxia, mental retardation, quadrupedal locomotion syndrome (CAMRQ2), and microcephaly." (PMID 30531936, 2021). "WDR81 (WD repeat-containing protein 81) is associated with cerebellar ataxia, mental retardation and disequilibrium syndrome (CAMRQ2, [MIM 610185])." (PMID 27390838, 2015). "WDR81 (WD repeat-containing protein 81) is associated with cerebellar ataxia, mental retardation and disequilibrium syndrome (CAMRQ2, [MIM 610185]), also referred to as Uner Tan syndrome." (PMID 27390838, 2015). "Importantly, WDR81 mutations were initially reported in a consanguineous family suffering from cerebellar ataxia, mental retardation, and quadrupedal locomotion syndrome (CAMRQ2), and later in patients with microcephaly." (PMID 30531936, 2021). "In contrast, ITPR1, PTPN1, SPTBN2, and WDR81 are known as cerebellar ataxia-related genes, and there is limited evidence of shared mechanisms with epilepsy." (PMID 37645600, 2023). "The condition has been classified into cerebellar ataxia, mental retardation and disequilibrium syndrome types 1 (CAMRQ1), 2 (CAMRQ2) and 3 (CAMRQ3) and attributed to mutations in VLDLR, CA8 and WDR81 genes, respectively." (PMID 22973972, 2012). "This case highlights the phenotypic variability of CAMRQ2 and underscores the importance of considering WDR81 variants in patients with cerebellar ataxia, even in the absence of consanguinity." (PMID 40013199, 2025).
microcephaly (5 papers, 2021 to 2025). A congenital or acquired developmental disorder in which the circumference of the head is smaller than normal for the person's age and sex. "WDR81 functions are associated with autophagy, endosomal trafficking, and its loss of function causes severe microcephaly in patients." (PMID 40894729, 2025). "Here, we investigate the consequences of WDR81 loss of function, which causes severe microcephaly in patients." (PMID 35013230, 2022). "In this study, we investigated the mechanisms by which mutation in the WDR81 gene leads to severe microcephaly in patients." (PMID 35013230, 2022). "Particularly, dysregulation of neurogenesis and neural development are likely responsible for the pathology of WDR81 mutation-associated CAMRQ2 and microcephaly." (PMID 30531936, 2021). "Mutations in the human WDR81 gene result in severe microcephaly." (PMID 35013230, 2022). "Mutations of WDR81 are associated with neurological disorders including CAMRQ2 and microcephaly." (PMID 30531936, 2021). "Overall, mice knocked out for WDR81 have reduced brain size and altered neuronal positioning, largely recapitulating the microcephaly and lissencephaly phenotypes reported in humans." (PMID 35013230, 2022). "WDR81‐related neurological diseases including autosomal recessive CAMRQ2, microcephaly and HYC3." (PMID 33724704, 2021).
viral infection (4 papers, 2021 to 2025). "We have previously reported that expression of human WDR81 in ΔWDR81 MEFs restores virus infection and virus-induced cell death." (PMID 41042063, 2025). "Additionally, autophagy genes IFI16, ZC3H12A, SQSTM1, WDR81, and PIK3R2 are associated with viral infection, including SARS-CoV-1 and were downregulated in this study when cells were treated with NIC." (PMID 37901834, 2023). "Other genes that were down-regulated with viral infection (GOLGA2, IFI16, WDR81, HK2, SQSTM1, ULK1) remained down-regulated with NIC treatment (with and without virus)." (PMID 37901834, 2023). "As per viral infection, NIC and virus treated cells (at 48 h) also saw an up-regulation of GABARAPL1, MAP1LC3A, USP30, BMF, and TBK1; WDR81 was also down-regulated in the NIC and virus treatment at 48 h." (PMID 37901834, 2023). "Genes for the endosomal entry-specific enzyme CTSL and for regulating endolysomal trafficking and membrane fusion, such as NPC1/2 and WDR81/91, were identified and required for Sdel, but not for Sfull virus infection in A549 cells." (PMID 33574281, 2021).
colorectal cancer (2 papers, 2014 to 2015). A primary or metastatic malignant neoplasm that affects the colon or rectum. "WDR81 has also been found to be mutated in >10 % of the colorectal cancer cell lines." (PMID 27390838, 2015). "WDR81 has been found to be mutated in >10 % of the colorectal cancer cell lines and SERPINF2-WDR81 loci was reported to be one of the six significant loci for serum albumin as a result of transethnic meta-analysis." (PMID 27390838, 2015). "Although the remaining 7 genes (PKD1, FAM38A, WDR81, TMEM136, SLC36A1, SLC26A6, IGFLR1) are mutated in >10% of the colorectal cancer cell lines, literature searches did not reveal evidence of the functional role or therapeutic potential of these genes in colorectal cancer." (PMID 25193853, 2014).
reovirus infection (2 papers, 2022 to 2025). "Susceptibility to reovirus infection was restored by complementing KO cells with human WDR81." (PMID 35320319, 2022). "In this study, we uncovered that WD repeat-containing protein 81 (WDR81) is required for apoptosis induction after reovirus infection." (PMID 41042063, 2025). "Further, our data suggest a previously unidentified role for WDR81 in impacting reovirus-induced cell death or a role for WDR81 in supporting events in reovirus infection, which ultimately affect reovirus-induced cell death." (PMID 35320319, 2022). "Using a CRISPR-Cas9 screen, we identified WD repeat-containing protein 81 (WDR81) as a host factor required for efficient reovirus infection of murine cells." (PMID 35320319, 2022). "To evaluate the function of WDR81 in reovirus infection, we used CRISPR-Cas9 editing to generate WDR81-deficient MEFs." (PMID 35320319, 2022). "Because WDR81 directly affects the early events in infection, the increased survival of ΔWDR81 cells to reovirus infection is at least in part related to the inability of these cells to support reovirus infection." (PMID 35320319, 2022). "Notably, CRISPR-mediated KO of WD repeat-containing protein 81 (WDR81) rendered cells resistant to reovirus infection." (PMID 35320319, 2022). "To ensure that the observed defect in reovirus infection was due to the genetic ablation of WDR81, we transduced ΔWDR81 cells with an empty lentivirus or a lentivirus that confers expression of 2xHA-tagged human WDR81 (hu-WDR81), which shares 88% homology with murine WDR81." (PMID 35320319, 2022). "We previously identified a function for a host protein, WD repeat-containing protein 81 (WDR81), in reovirus infection." (PMID 41042063, 2025). "In addition to WDR81 and WDR91, our screen uncovered two other proteins, Rab7 and CCZ1, that are required for endosomal maturation and reovirus infection." (PMID 35320319, 2022). "For the purpose of this study, we did not evaluate if the absence of WDR81 influences cell death independent of the capacity to allow reovirus infection." (PMID 35320319, 2022). "Interestingly, WDR81 interacts with WDR91, which was also identified in our work and in another screen for proviral factors of reovirus infection." (PMID 35320319, 2022).
Anxiety (1 paper, 2021). Intense feelings of nervousness, tension, or panic often arise in response to interpersonal stresses. "Taken together, these behavioral assessments suggest that selective deletion of Wdr81 in aNPCs leads to impaired hippocampus-dependent learning, but does not result in abnormal locomotor activity or overt anxiety-like behavior." (PMID 30531936, 2021).
CAMRQ syndrome (1 paper, 2025). "CAMRQ syndrome can arise from pathogenic variants in several genes including the very low‐density lipoprotein receptor (VLDLR) (CAMRQ1; MIM: 224050), WD repeat domain 81 (WDR81) (CAMRQ2; MIM: 610185), carbonic anhydrase 8 (CA8) (CAMRQ3; MIM: 613227) and ATP8A2 designated as CAMRQ4 (MIM: 615268)." (PMID 39931767, 2025).
cervical cancer (1 paper, 2023). A primary or metastatic malignant neoplasm involving the cervix. "In addition, WDR81 expression was high in skin cancer and myeloma and, conversely, low in diseases such as cervical cancer and teratoma." (PMID 36593250, 2023).
fibrosarcoma (1 paper, 2025). A malignant mesenchymal fibroblastic neoplasm affecting the soft tissue and bone. "To assess the impact of WDR81 in other cell types, we compared cell death induction by ABT-737 and TNF-CHX in control and WDR81-deficient HT1080 cells, a human fibrosarcoma cell line." (PMID 41042063, 2025).
Hydrocephalus (1 paper, 2021). Hydrocephalus is an active distension of the ventricular system of the brain resulting from inadequate passage of CSF from its point of production within the cerebral ventricles to its point of absorption into the systemic circulation. "We identified a fetus with a Novel compound heterozygous frameshift variants in WDR81(c.146_147insG (p.Thr52fs) and c.673delC (p.Leu225fs)) presented with the main Congenital hydrocephalus 3 with brain anomalies (HYC3)." (PMID 33724704, 2021). "We suggested fetal hydrocephalus with extracerebral manifestations may be suggestive of WDR81 or other hydrocephalus‐related genes deficiency, and WES should be triggered for achieving a diagnosis." (PMID 33724704, 2021). "We suggested that fetal hydrocephalus with extracerebral manifestations may be suggestive of WDR81 deficiency and WES is effective for achieving a conclusive diagnosis for disorder." (PMID 33724704, 2021). "Nonsyndromic hydrocephalus includes the classical X‐linked type associated with mutations in L1CAM (MIM 307000) and autosomal recessive hydrocephalus related to the gene CCDC88C (HYC1, MIM 236600), MPDZ (HYC2, MIM 615219), and WDR81 (HYC3, MIM 617967)." (PMID 33724704, 2021).
infection (7 papers, 2011 to 2025). The state of being infected such as from the introduction of a foreign agent such as serum, vaccine, antigenic substance or organism. "Thus, reovirus cannot launch infection from endocytic vesicles that are disrupted by the loss of WDR81 or NPC1." (PMID 35320319, 2022). "Previous work demonstrated that WDR81 is essential for infection by reovirus virions but dispensable for infection by ISVPs, an entry intermediate generated via in vitro chymotrypsin digestion of virions." (PMID 41042063, 2025). "We demonstrate that even though WDR81 is dispensable for infection by reovirus ISVPs, it is required for ISVP-induced apoptosis." (PMID 41042063, 2025). "Because ΔWDR81 cells fail to undergo cell death following infection by ISVPs, our results suggest that WDR81 is required for efficient induction of apoptosis." (PMID 41042063, 2025). "Whereas NT cells succumbed to VSV-EBO GP (GFP) infection within 26 h, the viability of CTSL- and WDR81-deficient cells was unaffected." (PMID 35320319, 2022). "To determine whether WDR81 is also required for infection by VSV-EBO GP (GFP), we quantified the appearance of GFP-positive cells over time." (PMID 35320319, 2022). "Though WDR81 was dispensable for infection by VSV (vesicular stomatitis virus), which exits the endosomal system at an early stage, it was required for VSV-EBO GP (VSV that expresses the Ebolavirus glycoprotein), which must reach the late endosome to initiate infection." (PMID 35320319, 2022). "We next investigated whether the VPS29/CCC complex and the WDR81/91 were required for infection by a diverse panel of respiratory viruses, including coronaviruses." (PMID 35229640, 2022). "Remarkably, these steps only require WDR81 when infection is initiated by virions." (PMID 35320319, 2022). "Editing of these genes, including those encoding CTSL, cholesterol transporters NPC1/2, WDR81/91, and TFE3, markedly reduced infection, suggesting that Sdel and SARS-CoV may utilize similar entry machinery in this cell type." (PMID 33574281, 2021). "Many of the hits were associated with intracellular transport or endosome activity, including VPS29, the CCDC22/CCDC93/COMMD3 (CCC) complex, and the WDR81/91 complex, suggesting a requirement for these functions in HCoV-OC43 infection." (PMID 35229640, 2022). "We show that infection by reovirus is dependent upon WDR81; in its absence, ISVPs are generated but do not continue the infectious cycle." (PMID 35320319, 2022). "Since virus production from ΔWDR81 cells remained low over an extended time frame, these data suggest that infection is not simply slower in the absence of WDR81." (PMID 35320319, 2022). "Together, our data support the idea that the reduced capacity of virions to launch infection is related to their accumulation in a non-productive compartment due to the absence of WDR81." (PMID 35320319, 2022). "Our results indicate that VSV-EBO GP (GFP), which follows the entry pathway of native Ebolavirus, fails to efficiently initiate infection in the absence of WDR81." (PMID 35320319, 2022). "Infection with lenti-CreGFP, but not lenti-dCreGFP, led to ablation of WDR81 expression in Wdr81f/f aNPCs." (PMID 30531936, 2021). "Since WDR81-deficient cells have constitutively high IKK-NFκB activity, they allow us to explore the biological effect of not being able to effectively block NFκB later in infection." (PMID 41042063, 2025). "Based on our observation that infection by virions is blocked by the absence of WDR81 and infection by ISVPs is not, we hypothesized that WDR81 is required for the entry of other viruses that must transit through the late endosome to initiate infection." (PMID 35320319, 2022). "Moreover, in 293T-ACE2 cells, KO of the CCC complex inhibited HCoV-OC43 but not HCoV-NL63 or rVSV/SARS-CoV-2 infection, while WDR81/91 knockout impaired infection for all three viruses." (PMID 35229640, 2022).
infection (continued). "We find that infection with VSV-EBO GP (GFP), which mimics the cell entry pathway of native Ebolavirus, is diminished by the absence of WDR81." (PMID 35320319, 2022).
tumor (3 papers, 2019 to 2024). "In this study, HNRNPH1 and WDR81 were highly expressed in OTSCC tumor samples and were protective genes for predicting prognosis." (PMID 36593250, 2023).
neurological diseases (2 papers, 2021). "Together these findings provide mechanistic explanations for WDR81-associated neurological disorders." (PMID 30531936, 2021). "The underlying mechanism of WDR81 caused neurological diseases still need to elucidate." (PMID 33724704, 2021). "Of note, our findings that pharmacological inhibition of PI3K-III and SARA-dependent TGFβ signaling markedly ameliorated the defective neurogenesis caused by Wdr81 deficiency offer potential therapeutic strategies for treating the mental illness seen in WDR81-associated neurological disorders." (PMID 30531936, 2021). "Taken together, these findings not only uncover the requirement for the WDR81–SARA–TGFβ axis in adult hippocampal neurogenesis, but also suggest that defective adult hippocampal neurogenesis contributes to the etiology of WDR81-related neurological diseases." (PMID 30531936, 2021).
cancer (1 paper, 2023). A tumor composed of atypical neoplastic, often pleomorphic cells that invade other tissues. "Our sequencing results for WDR81 and HNRNPH1 are consistent with the mRNA expression interval of the CCLE pan-cancer spectrum results." (PMID 36593250, 2023).
WDR81 also shares sentences with these, for which no sentence is quoted: Intellectual disability (2 papers); Cerebellar hypoplasia (1); colorectal tumors (1); congenital hydrocephalus (1); dengue (1); development (1); developmental delay (1); Dysequilibrium syndrome (1); epilepsy (1); hydranencephaly (1); hydrops fetalis (1); Lissencephaly (1); lymphoma (1); macroglossia (1); mental illness (1); myeloma (1); neurodevelopmental disorder (1); skin cancer (1); Strabismus (1); teratoma (1).